RNF40 (ring finger protein 40)
Description:
Component of the RNF20/40 E3 ubiquitin-protein ligase complex that mediates monoubiquitination of 'Lys-120' of histone H2B (H2BK120ub1). H2BK120ub1 gives a specific tag for epigenetic transcriptional activation and is also prerequisite for histone H3 'Lys-4' and 'Lys-79' methylation (H3K4me and H3K79me, respectively). It thereby plays a central role in histone code and gene regulation. The RNF20/40 complex forms a H2B ubiquitin ligase complex in cooperation with the E2 enzyme UBE2A or UBE2B; reports about the cooperation with UBE2E1/UBCH are contradictory. Required for transcriptional activation of Hox genes. (Microbial infection) Promotes the human herpesvirus 8 (KSHV) lytic cycle by inducing the expression of lytic viral genes including the latency switch gene RTA/ORF50.
Synonyms: RBP95; BRE1B; KIAA0661; STARING
Tractability: PROTAC: UniProt records ubiquitination sites on it; ubiquitination databases record sites on it; its protein half-life has been measured.
Gene: Protein-coding gene on chromosome 16 (30,761,745 to 30,776,307, forward strand). Ensembl gene ENSG00000103549.
Subcellular location: Nucleus
Subcellular location (Human Protein Atlas): Nucleoplasm
Pathways (Reactome):
Metabolism of proteins: E3 ubiquitin ligases ubiquitinate target proteins
Gene Ontology:
Molecular function: mRNA 3'-UTR binding; protein binding; protein homodimerization activity; ubiquitin protein ligase binding; ubiquitin-protein transferase activity; ubiquitin protein ligase activity; metal ion binding
Biological process: positive regulation of transcription by RNA polymerase II; regulation of DNA-templated transcription; regulation of mitotic cell cycle; ubiquitin-dependent protein catabolic process; protein ubiquitination
Cellular component: BRE1 E3 ubiquitin ligase complex; HULC complex; membrane; nucleoplasm; nucleus; ubiquitin ligase complex
Genetic constraint (gnomAD): Loss-of-function variants: 39 observed, 125.64 expected, observed/expected ratio (o/e) 0.31, 90% interval 0.24 to 0.41. The upper end of that interval is the gene's LOEUF score, 0.41, which puts it in group 1 of 6, group 1 being the genes least tolerant of losing a copy. Missense variants: 1,003 observed, 1,354.1 expected, observed/expected ratio (o/e) 0.74, 90% interval 0.7 to 0.78. Synonymous variants: 538 observed, 540.35 expected, observed/expected ratio (o/e) 1, 90% interval 0.93 to 1.07.
Gene-disease validity (ClinGen):
ClinGen rates the evidence that RNF40 causes each of these diseases.
congenital heart disease (autosomal dominant): Limited. A heart disease that is present at birth.
Homologues: Orthologues: chimpanzee RNF40 (99% identical), macaque RNF40 (98% identical), rabbit RNF40 (96% identical), guinea pig RNF40 (95% identical), pig RNF40 (94% identical), rat Rnf40 (93% identical), mouse Rnf40 (93% identical), dog RNF40 (92% identical), tropical clawed frog rnf40 (69% identical), zebrafish rnf40 (68% identical), Drosophila melanogaster Bre1 (46% identical), Caenorhabditis elegans rfp-1 (22% identical). Paralogues in human: RNF20 (58% identical).
Diseases named in the same sentence as RNF40 in open-access papers:
RNF40 is named in the same sentence as 29 diseases in open-access papers, as found by Europe PMC text mining. Sharing a sentence is not in itself a finding about the gene and the disease. The quoted sentences say what the papers report.
breast carcinoma (11 papers, 2016 to 2025). "They discovered that a loss-of-function of RNF20/RNF40 resulted in G2/M arrest and apoptosis by downregulating the motor protein Eg5 in the human breast cancer cell line MCF-7." (PMID 31266541, 2019). "Finally, the genetic model for Rnf40 loss in endogenous HER2-driven mammary carcinomas used in this study supported the human patient data, arguing for a tumor-supporting role for RNF40 in HER2-dependent BC." (PMID 33070155, 2020). "One study reported that the knockdown of the H2B ubiquitin ligase Rnf40 reduced ERα‐induced transcription and activated the signaling pathways associated with estrogen‐dependent cell proliferation and cell survival, thereby exerting a tumor‐suppressive role in breast cancer." (PMID 39777866, 2025). "Past observations made in hepatocellular carcinoma, mixed-lineage leukemia (MLL), HER2-driven mammary carcinoma, colorectal cancer and TNBC demonstrated an association between high RNF20 and RNF40 levels and worse cancer disease outcomes." (PMID 40597205, 2025). "In breast cancer, however, both oncogenic and tumor-suppressive roles of RNF40 have been reported, raising the question: friend or foe?" (PMID 33199825, 2021). "The importance of RNF40-mediated ERα regulation in breast cancer has been investigated in this context." (PMID 33199825, 2021). "Motivated by the expectation that additional nonhistone target proteins of RNF20/40 exist, we are currently seeking to identify EMT-TF-related proteins ubiquitylated by RNF20/40 or RNF40 in breast cancers." (PMID 33199825, 2021). "In support of a pro-oncogenic role for RNF40, a recent random amplified polymorphic DNA analysis demonstrated DNA amplification at the genomic locus of RNF40 in breast cancer tissues." (PMID 33199825, 2021). "In this study, we utilized human tumor samples, cell culture models, and a mammary carcinoma mouse model with tissue-specific Rnf40 deletion and identified an unexpected tumor-supportive role of RNF40 in HER2+-BC." (PMID 33070155, 2020). "Our studies using a tissue-specific transgenic and gene ablation approach demonstrate for the first time that RNF40 exerts a profound tumor-supportive function in HER2-driven mammary carcinoma." (PMID 33070155, 2020). "Taken together, these results demonstrate that RNF40 plays an essential role in HER2-driven mammary tumor initiation and progression." (PMID 33070155, 2020). "In this regard, high H2BK120ub1 levels and RNF20/RNF40 expression promote expression of ER target genes and proliferation of luminal breast cancer cells." (PMID 30781493, 2019). "The staining of Eg5 (median H score, 299), RNF20 (median H score, 274), and RNF40 (median H score, 272) was much stronger in 99 breast carcinoma tissues than the staining of these proteins in 10 adjacent normal breast tissues (median H score,<20)." (PMID 27557628, 2016). "Current research on Rnf40 primarily focuses on its role in breast cancer." (PMID 39777866, 2025). "Particularly, loss or low expression of RNF40 is negatively correlated with the expression levels of genes enriched in glycolysis, which supports a pivotal role of RNF40 in maintaining the glycolytic program and promoting the malignant behavior of breast cancer." (PMID 38909032, 2024). "For example, suppressor of Ty 6 homolog (SUPT6H), a histone chaperone and transcription elongation factor, was found to be required for estrogen-mediated transcription and maintenance of chromatin structure in breast cancer cells, likely through interaction with RNF40 and regulation of H2Bub1." (PMID 33199825, 2021). "Tumor-suppressive roles of RNF40 have been reported in breast cancer cells." (PMID 33199825, 2021). "This suggests a concurrent upregulation of RNF20, RNF40, and Eg5 in breast cancer." (PMID 27557628, 2016). "This contrasts with the roles of these proteins in breast cancer cells, where both RNF20 and RNF40 promote carcinogenesis." (PMID 40436847, 2025).
breast carcinoma (continued). "This important work highlights the opportunity for therapeutic intervention that targets RNF40 and/or H2Bub1 in the HER2+ breast cancer subtype." (PMID 33233707, 2020). "In this regard, the RNF20 promoter is hypermethylated in breast cancer and reduced expression of RNF20 and/or RNF40 is observed in seminoma, basal-like breast cancer, and colorectal cancer." (PMID 30781493, 2019). "Collectively, this work demonstrates a previously unknown essential role of RNF40 in HER2+-BC, revealing the H2B monoubiquitination axis as a possible tumor context-dependent therapeutic target in breast cancer." (PMID 33070155, 2020).
osteosarcoma (6 papers, 2023 to 2025). A usually aggressive malignant bone-forming mesenchymal neoplasm, predominantly affecting adolescents and young adults. "Furthermore, ALKBH5-mediated m6A deficiency increases the expression of USP22 and RNF40 in osteosarcomas, promoting osteosarcoma cell growth and proliferation." (PMID 40001461, 2025). "In osteosarcoma, an m6A modification disorder led to increased expression of the ubiquitin ligase RNF40, resulting in unchecked replication." (PMID 37229206, 2023). "Notably, RNA demethylase ALKB Homolog 5 (ALKBH5)-mediated m6A deficiency in osteosarcoma leads to increased expression of USP22 and RNF40, suppressing H2A ubiquitination and promoting gene expression related to replication and DNA repair, driving osteosarcoma progression." (PMID 39048965, 2024).
colorectal cancer (5 papers, 2019 to 2025). A primary or metastatic malignant neoplasm that affects the colon or rectum. "Of note, RNF40 has been implicated in the control of key apoptotic genes in colorectal cancer cells." (PMID 33233707, 2020). "In this study, we were able to demonstrate that the knockdown of the E3 ligase RNF40 and, consequently, the loss of H2Bub1 results in reduced tumorigenic potential and increased apoptosis in human colorectal cancer cells in vitro." (PMID 31266541, 2019). "A low frequency of RNF20 and RNF40 mutations have been reported in colorectal cancer." (PMID 33233707, 2020). "Together, our findings suggest that RNF40 exerts pro-tumorigenic functions in colorectal cancer in vitro by increasing clonogenic potential as well as by suppressing apoptosis." (PMID 31266541, 2019). "Further experimental procedures will help to elucidate further underlying molecular mechanisms employed by RNF40 to reduce apoptotic signaling and to determine whether RNF40 may serve as a therapeutic target for inducing apoptosis in colorectal cancer cells." (PMID 31266541, 2019). "Our previous studies suggested that RNF40 might be required for the pro-proliferative behavior of colorectal cancer cells in vitro." (PMID 31266541, 2019).
prostate carcinoma (4 papers, 2018 to 2023). A carcinoma that arises from epithelial cells of the prostate gland. "In addition to association with ERα and regulation of ER target genes, RNF20 and RNF40 have been shown to physically associate with the AR, with the H2Bub1/RNF20/RNF40 axis implicated in AR-associated gene transcription and affecting the growth of prostate cancer cells." (PMID 33233707, 2020). "Concordantly, RNF20, RNF40 and H2Bub1 were also found to correlate with poor prognosis in hepatocellular carcinoma and to support the tumorigenic properties of prostate cancer and MLL-rearranged lymphoblastic leukemia." (PMID 37770435, 2023). "For example, siRNA (short interfering RNA) down-regulation of RNF20 and RNF40 has been reported to inhibit proliferation of prostate cancer cells." (PMID 33233707, 2020). "RNF40 has been reported as an oncogene in prostate cancer, liver cancer, and MALL." (PMID 33199825, 2021). "In contrast, our group and others recently identified unexpected critical tumor-supportive functions of the RNF40/H2Bub1-axis in specific cancer types such as mixed-lineage leukemia (MLL), ER+-BC, HER2+-BC, colorectal and prostate cancer." (PMID 37770435, 2023).
inflammatory bowel disease (3 papers, 2021 to 2025). A spectrum of small and large bowel inflammatory diseases of unknown etiology. "Meanwhile, Rnf40 also plays a crucial role in conditions such as inflammatory bowel disease, type‐1 diabetes, and cancer‐associated osteolysis." (PMID 39777866, 2025). "Moreover, Rnf40 plays a crucial role in the pathogenesis of multiple diseases, including inflammatory bowel disease, cancers, and cancer‐associated osteolysis, highlighting its potential as a therapeutic target." (PMID 39777866, 2025). "In intestinal inflammation of inflammatory bowel disease (IBD) patients and mouse models, the loss of H2Bub1 following intestinal Rnf20 or Rnf40 deletion resulted in decreased H3K4me3 occupancy in the transcribed region of various IBD‐associated genes." (PMID 40522008, 2025).
lung carcinoma (2 papers, 2022 to 2025). "In contrast to RNF20 loss, which markedly promoted cell growth and migration, RNF40 depletion had minimal impact, suggesting distinct roles for these proteins in lung epithelial and lung cancer cells." (PMID 40436847, 2025). "Notably, RNF40 depletion had minimal impact on the cell growth and migration of lung epithelial cells, suggesting that RNF20 and RNF40 have distinct, independent roles in lung cancer development and progression." (PMID 40436847, 2025).
acute lymphoblastic leukemia (1 paper, 2021). Leukemia with an acute onset, characterized by the presence of lymphoblasts in the bone marrow and the peripheral blood. "RNF40 has been reported as a tumor suppressor in colorectal cancer (CRC), but has also been reported as an oncogene in other cancers, including prostate and liver cancers, and MLL-rearranged acute lymphoblastic leukemia (ALL)." (PMID 33199825, 2021).
autism spectrum disorder (1 paper, 2022). A spectrum of developmental disorders that includes autism, and Asperger syndrome. "In addition, RNF40 located at the 16p11.2 region was associated with the risperidone response in children with autism spectrum disorders." (PMID 36618913, 2022).
cervical cancer (1 paper, 2025). A primary or metastatic malignant neoplasm involving the cervix. "Despite its well-established significance in various malignant diseases, the role of RNF20 and RNF40 in cervical cancer remains poorly understood." (PMID 40597205, 2025). "We showed that high RNF20 and RNF40 levels correlate with cervical cancer cell aggressiveness and poor patient prognosis." (PMID 40597205, 2025). "Together, our results indicate that interfering with RNF20 and RNF40 driven H2Bub1 and the peroxisome transcriptional program could provide a novel target for a therapeutic approach against aggressive cervical cancer." (PMID 40597205, 2025).
Cognitive impairment (1 paper, 2025). Abnormal cognition is characterized by deficits in thinking, reasoning, or remembering. "We aimed to investigate the role of Rnf40 in hypertension‐induced cerebrovascular endothelial barrier dysfunction and cognitive impairment." (PMID 39777866, 2025).
colitis (1 paper, 2021). Inflammation of the colon. "Several of these common RNF20/RNF40/VDR targets were shown to be downregulated in experimental colitis, such as Muc2." (PMID 34088983, 2021). "Using this model to delete Rnf40 resulted in a sporadic loss of RNF40 and H2Bub1 staining in only 15% of colorectal epithelial cells and paradoxically elicited a protective effect during DSS-induced colitis." (PMID 34088983, 2021). "Finally, we sought to determine whether gene expression patterns altered following Rnf20 and Rnf40 deletion in IECs may be relevant for murine models for colitis and human IBD." (PMID 34088983, 2021). "In contrast, mice heterozygous for Rnf20 or Rnf40 deletion did not develop spontaneous inflammation and did not display increased sensitivity to DSS-mediated colitis." (PMID 34088983, 2021).
colorectal tumors (1 paper, 2019). "However, our own data demonstrated that colorectal tumors display a high degree of heterogeneity in H2Bub1 levels, while RNF40 amounts were constant in cancer lesions, thereby suggesting that RNF40 may play additional roles in CRC apart from the monoubiquitination of H2B." (PMID 31266541, 2019).
Hypertension (1 paper, 2025). The presence of chronic increased pressure in the systemic arterial system. "Collectively, our findings provide evidence that Rnf40 directly inhibits mitophagy by ubiquitinating and degrading Parkin, a key mechanism underlying hypertension‐induced dysfunction in cerebrovascular endothelial barriers." (PMID 39777866, 2025). "To address these gaps in the literature, in this study, we aimed to investigate the role of Rnf40 in hypertension‐induced cerebrovascular endothelial barrier dysfunction and cognitive performance." (PMID 39777866, 2025). "The results indicated that Rnf40 silencing effectively mitigated hypertension‐induced cognitive dysfunction." (PMID 39777866, 2025). "Our findings suggest that increased Rnf40 levels exacerbate hypertension‐induced cerebrovascular endothelial barrier dysfunction by ubiquitinating Parkin." (PMID 39777866, 2025). "To understand the role of RNF40 in hypertension‐induced cerebrovascular endothelial cell damage, we used pAAV‐hFLT1‐MCS‐EGFP‐3×Flag‐mir30shRnf40 to establish an Rnf40‐deficient model in spontaneously hypertensive rats (SHRs)." (PMID 39777866, 2025). "Schematic diagram of the mechanism that Rnf40 exacerbates hypertension‐induced cerebrovascular endothelial barrier dysfunction (Created in BioRender." (PMID 39777866, 2025). "To elucidate the role of RNF40 in hypertension‐induced cerebrovascular endothelial cell damage, we established an Rnf40‐depleted model in SHRs." (PMID 39777866, 2025). "Additionally, more specific techniques are required to precisely reduce Rnf40 expression in cerebrovascular endothelial cells in vivo to further clarify its role in hypertension‐induced cerebrovascular endothelial barrier dysfunction." (PMID 39777866, 2025). "Knocking down Rnf40 could effectively reverse this process, thereby improving hypertension‐induced cerebrovascular endothelial barrier dysfunction and cognitive performance." (PMID 39777866, 2025).
liver cancer (1 paper, 2021). An epithelial or non-epithelial malignant neoplasm that arises from the liver. "Thus, RNF40 might function as a tumorigenic factor in liver cancer." (PMID 33199825, 2021).
neuroblastoma (1 paper, 2020). Neuroblastoma (NB) is the most common solid, extracranial childhood tumor. "For this purpose, we analyzed the ability of ectopic Egr2 to induce the expression of its target genes in Neuro2a neuroblastoma cells with varying levels of Rnf40/Rnf20 E3 ligase activity." (PMID 32672815, 2020).
schizophrenia (1 paper, 2017). A major psychotic disorder characterized by abnormalities in the perception or expression of reality. "Interestingly, RNF40 is located at 16p11.2, a region implicated in both ASD and schizophrenia, and RNF40 and RNF213 have RING domains (Really Interesting New Gene domains (RING)) which contain zinc binding sites." (PMID 28870209, 2017).